STAT3 (signal transducer and activator of transcription 3)
Diseases named in the same sentence as STAT3 in open-access papers (continued):
Sharing a sentence is not in itself a finding about the gene and the disease.
glioma (continued). "This traditional preparation promotes the pyroptosis of glioma cells via the POU4F1/STAT3 axis and effectively halts glioma proliferation, although its precise mechanisms and clinical applicability warrant further investigation." (PMID 39184045, 2024). "We subsequently quantified the levels of IL-6 and IL-8 secreted in the supernatant using ELISA after two hours of TNF treatment of glioma cells, as STAT3 was observed to be upregulated at that time point." (PMID 38561856, 2024). "The expression of selected hypoxia related factors including STAT3 was evaluated in a time series of formalin fixed paraffin embedded and cryopreserved glioma samples from repeatedly resected patients." (PMID 38654280, 2024). "The expression of β-catenin, p-JAK-2, and p-STAT3 in normal human brain tissue was much lower than that in glioma tissues." (PMID 38397980, 2024). "The hypoxic glioma-derived exosome miRNA-1246 promotes glioma proliferation, migration, and invasion in vitro and in vivo by inhibiting the NF-κB signaling pathway, activating the STAT3 signaling pathway and inducing M2 macrophages polarization." (PMID 39065562, 2024). "In glioma stem cells, inhibiting gp130 can attenuate IL-6-induced p-STAT3 expression, thereby inhibiting tumour growth." (PMID 38504172, 2024). "And in our study, we found that the mRNA expression levels of IL-6, TNF-α, and STAT3, which are important factors in the STAT3 signaling pathway, were significantly increased in glioma samples." (PMID 38495483, 2024). "In our investigation, we found that the knock-down of STAT3 suppressed the growth and mediated apoptosis, which effects similar to that in glioma cells when miR-410 overexpression." (PMID 38238515, 2024). "Future experiments should investigate the role of STAT3 downstream of CD114 in different glioma types." (PMID 38474265, 2024). "In contrast, the mechanism of action of BCL3 in controlling apoptosis in glioma cells was defined as a STAT3 mediated regulation of BCL2 and Mcl1 while suppression of BCL3 reduced xenograft tumour growth." (PMID 38195591, 2024). "In this regard, we analyzed GCSF, GCSFR and STAT3 gene expressions between tumour-associated normal tissue (TANT) and IDH-wild type, (CNS WHO grade 4) glioma (GBM) resulting in statistically significant differences in their expressions." (PMID 38538691, 2024). "Among others, STAT3 promotes CASC9 expression, essential lncRNA in glioma cells, which upregulates the expression of STAT3 via sponging miR-519d, generating a positive feedback loop of STAT3/CASC9/miR-519d." (PMID 39188680, 2024). "WP1066, a STAT3 pathway inhibitor, can penetrate the blood–brain barrier and is currently undergoing phase I clinical trials for adult recurrent glioma, metastatic melanoma, and high‐grade pediatric brain tumors." (PMID 38605477, 2024). "Prior study revealed that CCN1 enhanced the migration and invasion of glioma cells dependence on binding to integrins and activating downstream of STAT3 pathway." (PMID 39659236, 2024). "It was demonstrated that inhibition of STAT3 enhances pro-inflammatory potential of these cells, which results in suppression of tumor growth in a murine model of glioma." (PMID 38499808, 2024). "Depletion of TRIM24 in glioma stem cells significantly reduced both p-STAT3 levels and cell proliferation, mirroring a similar phenotype observed in nasopharyngeal carcinoma cells." (PMID 39160596, 2024). "Collectively, the outcomes indicate that miR-410 exerts a suppressive impact on the growth of glioma, in part, by directing its focus towards STAT3." (PMID 38238515, 2024). "A similar phenomenon was observed with miR-21, as β-catenin, an essential substrate of γ-secretase, regulated miR-21 expression through STAT3 and promoted invasion in glioma cells." (PMID 38338859, 2024). "Many studies had emphasized that calcium signaling contributed to the progression of several cancer types (e.g., glioma, prostate, and breast) through the activation of STAT3." (PMID 38836117, 2024).
glioma (continued). "A study suggested that overexpression of circHIPK3 promotes the proliferation and invasive ability of glioma cells through sponge miR- 124-3p upregulation of signal transducer and activator of STAT3 levels." (PMID 39698112, 2024). "Glioma-derived exosomes enriched in IL-6 and miR-155-3p initiate autophagy and promote M2 polarization in TAMs through the IL-6-p-STAT3-miR-155-3p-autophagy-p-STAT3 positive feedback loop, enhancing glioma progression." (PMID 39430253, 2024). "Further experiments demonstrated the mediative role of miR-125a and its target gene STAT3 in NEAT1-induced polarization of M2-like macrophages that promote glioma progression." (PMID 39061140, 2024). "STAT3 is a critical mediator of tumorigenesis and tumor progression of glioblastoma, its activation induces cell proliferation, anti-apoptosis, glioma stem cell maintenance, tumor invasion, angiogenesis, and immune evasion." (PMID 38725860, 2024). "Our results suport the importance of STAT3 expression and activity in the context of hypoxia in malignant glioblastoma long-term surviving glioma patients while emphasizing heterogeneity of biological outcomes in varying employed tumor models." (PMID 38654280, 2024). "Our study demonstrated that lncRNA NEAT1 targets miR-125a to promote M2 macrophage polarization by directly upregulating STAT3 in glioma." (PMID 39061140, 2024). "As STAT3 is a transcription factor that promotes cell survival and proliferation when activated, inhibiting JAK2, and subsequently STAT3 allows resveratrol to exert growth-inhibitory effects on glioma cells." (PMID 39769099, 2024). "Studies showed that inhibiting JAK/STAT3 signaling can impede glioma cell proliferation, induce apoptosis, and enhance the sensitivity of tumor cells to conventional therapies." (PMID 39153914, 2024). "The results of this investigation indicate that miR-410 exerts direct regulatory control over STAT3 and suppresses its expression within glioma cells." (PMID 38238515, 2024). "The mRNA expression levels of important factors in the STAT3 signaling pathway in glioma samples and paracancerous samples were detected by RT-qPCR assay." (PMID 38495483, 2024). "In glioma tissues, there was an observed increase in STAT3 mRNA expression contrasted with their corresponding adjacent normal counterparts (P < 0.001)." (PMID 38238515, 2024). "According to previous research, EZH2 can regulate the phosphorylation level of STAT3 and activate pyroptosis in glioma cells through the inflammasome." (PMID 39069522, 2024). "Their preclinical study showed that the STAT3 inhibitor and irradiation reprogrammed the immunosuppressive glioma TME by improving DC maturation and interactions with T cells." (PMID 37279067, 2023). "Thereafter, it causes microglia to secrete more interleukin-6 (IL-6), which can result in binding glioma stem cells and their cell membrane receptors together, promoting the proliferation and growth of glioma stem cells through the IL-6/gp130/STAT3 pathway." (PMID 37280594, 2023). "Increased release of IL6 promotes migration and invasion of glioma cells through the activation of the transcription factor STAT3." (PMID 38293652, 2023). "Concurrent inhibition of EGFR and JAK2/STAT3 was highly effective in a panel of molecularly heterogeneous glioma stem cells (GSC) and in orthotopic EGFRvIII GSC xenografts." (PMID 36900355, 2023). "WP1066, which inhibits the activation of STAT3 by directly targeting JAKs, also suppresses glioma cells via NLRP3 inflammasome inhibition independently of STAT3 inhibition." (PMID 37723542, 2023). "With the combination of bioinformatic analysis and experimental validation, we identified that ARSD can promoted glioma progression by regulating JAK2/STAT3 pathway and M2 macrophage infiltration." (PMID 37766864, 2023). "Consistently, resveratrol (3,4′,5-tri-hydroxy-trans-stilbene) was reported to effectively improve the radiosensitivity of glioma by inhibiting STAT3 activity." (PMID 36923251, 2023).
glioma (continued). "ChIP-qPCR assays revealed that STAT3, present in nuclear lysates of glioma cells stimulated by constitutively activated STAT3, can bind to two GAS elements, respectively." (PMID 37642779, 2023). "Our present study discovered a novel signaling pathway of TRPM7/STAT3/FOSL1 axis that leads to glioma aggressiveness through stemness, suggesting novel therapeutic opportunities for the malignant disease." (PMID 37642779, 2023). "The intratumoral administration of the STAT3 ODN-decoy in the xenograft glioma model based on U251 cells reduced tumor growth by inhibiting cancer cell proliferation and stimulating their apoptosis." (PMID 38067351, 2023). "Combined with cell experiment and bioinformatic analysis, we found that ARSD can promote glioma progression through regulation of JAK2/STAT3 pathway and M2 macrophage infiltration." (PMID 37766864, 2023). "hnRNPA2/B1 is an oncogene in gliomas; inhibiting its expression leads to the inactivation of the AKT and STAT3 signaling pathways, which inhibit proliferation and enhance apoptosis in U251 glioma cells." (PMID 37964279, 2023). "Using CCK-8 and Transwel, we found the increased proliferation, migration, and invasion of glioma cells induced by ARSD overexpression were reversed upon inhibition of the JAK2/STAT3 signaling pathway with AG490." (PMID 37766864, 2023). "These cytokines upregulate transcription factors such as signal transducer and activator of transcription 3 (STAT3) in glioma cells, which subsequently triggers tumorigenic immune responses." (PMID 36969167, 2023). "In glioma cells, the phosphorylation of STAT3 and JAK2 is obviously increased, which contributes to the proliferation-promoting and the apoptosis-inhibiting in glioma cells." (PMID 37716993, 2023). "On the contrary, HOXC10 was positively associated with IL6/JAK/STAT3 and IL2/STAT5 signaling in glioma, and previous studies also indicated that these two signaling pathways were activated." (PMID 38154103, 2023). "These suggest that radiotherapy, although it can kill tumor cells, creates synergistic effects with activated STAT3 in the tumor immune microenvironment, recruiting immunosuppressive cells and enhancing radiation resistance in gliomas." (PMID 36923251, 2023). "Regardless, treatment with let-7a-1/d/f-1 decreases proliferation while increasing apoptosis and autophagy of glioma cells by binding to STAT3 mRNA 3′ UTR to decrease STAT3 expression." (PMID 37370851, 2023). "Previous studies reported that GDF15 is required for the activation of STAT3 and tumorigenesis in thyroid cancer and glioma stem cells." (PMID 36769245, 2023). "Aberrant STAT3 activation and highly phosphorylation positively correlate with the grades and poor prognosis of glioma, and are also involving in chemo‐resistance." (PMID 37308741, 2023). "In the current study, we found a new pathway that TRPM7 transactivates the FOSL1 gene through transcription factor STAT3 and enhances glioma stemness." (PMID 37642779, 2023). "Silencing KAT6B inhibits the enrichment of RNA polymerase II (RNA pol II) and histone H3 lysine 23 acetylation (H3K23ac) on the STAT3 promoter, while loss of STAT3 reverses KAT6B-induced inhibition of ferroptosis in glioma cells." (PMID 38072908, 2023). "Overall, pimozide shows promise as an agent that can inhibit glioma growth through STAT3 inhibition." (PMID 37998723, 2023). "Previous study explored the TMSB10 promoted glioma progression via YAP1/AKT/ERK1/2, but we explored the TMSB10 promoted glioma progression via IL6/JAK/STAT3 signaling pathway." (PMID 37275863, 2023). "STAT3 is a canonical transcription factor and persistent STAT3 activation affects cellular processes and target genes' transcriptions in gliomas." (PMID 37308741, 2023). "The results of the analysis of the area under the curve of the receiver operating characteristic curve further suggested that the expression of STAT3 is an effective way to evaluate the prognosis of patients with glioma." (PMID 37724127, 2023).
glioma (continued). "They additionally utilized Stattic and WP1066, small-molecule inhibitors of Stat3, and demonstrated the growth inhibition and cellular toxicity of G34R/V mutant glioma cells." (PMID 37509641, 2023). "In the current study, we investigated the role of TRPM7/STAT3/FOSL1 axis in promoting glioma stemness and gliomagenesis." (PMID 37642779, 2023). "The mutual activation between glioma cells can be inhibited by a nanomedicine (i.e., Nano-DOX), which inhibits STAT3 activation in glioma cells, thereby abolishing IL-6-mediated STAT3 cross-activation in astrocytes and its promotion of glioma cells." (PMID 36923251, 2023). "One of our findings shows that TRPM7 activates JAK2/STAT3 signaling pathways and leads to increased glioma cell proliferation and migration/invasion." (PMID 37642779, 2023). "In a co-culture system with astrocytes, glioma cells upregulated the expression of STAT3 target molecules (e.g., cell cycle protein D1, MMP2 and Bcl-2) that regulated anti-apoptosis, proliferation, and motility." (PMID 36923251, 2023). "In contrast, overexpression of PIAS3 in the U251-MG human glioma cell line inhibited the expression of the OSM-enhanced STAT3 target genes (e.g., Survivin, Bclxl, and SOCS3), which resulted in reduction of cell proliferation by 80%." (PMID 36923251, 2023). "For instance, resveratrol, a natural polyphenol with a stilbene structure derived from plants and fruits, has been shown to inhibit the proliferation and invasion of glioma cell in a STAT3-dependent manner." (PMID 36923251, 2023). "The area under curve results obtained by ROC curve analysis (1 year: 0.637, 3 years: 0.688, and 5 years: 0.714) further indicated that measuring the expression of STAT3 is an effective way to evaluate the prognosis of patients with glioma." (PMID 37724127, 2023). "Of interest, STAT3 expression (known as IL6/JAK/STAT3 signaling) in the glioma cell affects a variety of targeting genes and can propagate tumorigenesis by facilitating proliferation and angiogenesis." (PMID 36229714, 2023). "In vitro experiment showed that ARSD can promote glioma cell proliferation through JAK2/STAT3 pathway and regulate M2 macrophage infiltration." (PMID 37766864, 2023). "Our gene set enrichment analysis (GSEA) results revealed a significant enrichment of the STAT3 signaling pathway in high ZDHHC15 expression in glioma." (PMID 37161425, 2023). "Under hypoxic conditions, glioma-derived exosomes mediated their pro-tumor effects by activating STAT3 and inhibiting NF-κB signaling, with miRNA-1246 being the most enriched and also highly concentrated in the CSF of patients." (PMID 37700840, 2023). "These combined results demonstrated that TRPM7 induced FOSL1 transcriptional activation, which is mediated by the action of STAT3, a mechanism shown to be important in glioma stemness." (PMID 37642779, 2023). "For instance, glioma and medulloblastoma are linked to alterations in the JAK/STAT pathway, where STAT3 is the main deregulated STAT." (PMID 37446365, 2023). "In glioma or ovarian cancer models, Stat3 was phosphorylated both in cancer cells and macrophages by direct co-culture and promoted cancer cell proliferation and production of IL-6 or IL-10 from the macrophages." (PMID 37296952, 2023). "Our results demonstrate that ZDHHC15 plays a critical role in promoting the proliferation and migration of glioma cells via activation of the STAT3 signaling pathway." (PMID 37161425, 2023). "This effectively increased the efficiency of siRNA in silencing STAT3 and promoted apoptosis in glioma cells compared to free siRNA." (PMID 36923251, 2023). "Previous studies have found that GA-MSCs promote proliferation and maintain the stemness of glioma stem cells (GSCs) through the IL-6/gp130/STAT3 pathway." (PMID 37005685, 2023). "POSTN was reported to enhance the resistance of glioma stem cells to anti-angiogenic therapy by positively regulating VEGFA expression through activation of STAT3." (PMID 37461041, 2023).
glioma (continued). "Taken together, these data imply that NEDD4L carries out its effect on glioma by manipulating STAT3, which appears to be the downstream factor for the signaling pathway." (PMID 36618071, 2022). "Inhibition of STAT3 hinders tumor growth and induces apoptosis in gliomas in addition to suppression of TAM-activation." (PMID 35267626, 2022). "The cross-talk between NF-κB and STAT3 induces tumor progression and facilitates cancer stemness in gliomas." (PMID 36033456, 2022). "Phosphorylation of JAK2 activates STAT3 expression and induces abnormal proliferation of glioma cells, which finally leads to further deterioration of the disease and endangers life." (PMID 36065261, 2022). "IL10 binds to its corresponding receptor, causing STAT3 phosphorylation through JAK1 and STAT2, which stimulates the proliferation of glioma cells." (PMID 35741689, 2022). "Glioma cells secrete specific cytokines, thus creating an immunosuppressive environment involving signal transducer and activator of transcription 3 (STAT3) signaling, which inhibits immune cells." (PMID 36611945, 2022). "Another study focusing on TGF-β, a multifunctional polypeptide growth factor, showed that TGF-β-related glioma cells invasion required phosphorylation of STAT3 at the Y705 residue via IFITM3-STAT3 axis." (PMID 35409080, 2022). "The study identified eight co-downregulated miRNAs, three co-upregulated miRNAs, and seven genes associated with overall glioma survival, namely, KRAS, IFNB1, ALCAM, ERBB2, STAT3, FOSL1, and EN2." (PMID 36061185, 2022). "Mechanically, we identified that the expression of STAT3 was repressed by the KAT6B knockdown in glioma cells." (PMID 35432536, 2022). "It has been reported that an activity change in the IL6/JAK/STAT3 signaling pathway can regulate liver hepatocellular carcinoma, chronic myeloid leukemia, and glioma." (PMID 36118871, 2022). "The activation of IL6/JAK/STAT3 pathway between tumor-initiating cells and macrophages has been shown to lead to poor outcomes in glioma patients." (PMID 36341390, 2022). "Our previous study showed that PF inhibits human glioma cell proliferation by inhibiting the STAT3 pathway via regulating its turnover through the ubiquitination pathway." (PMID 36618071, 2022). "In future studies, researchers should investigate how exactly paeoniflorin promotes the degradation of STAT3 in glioma cells." (PMID 36046834, 2022). "Third, STAT3 is a transcription factor shown to physically interact with TET3 in human glioma cells." (PMID 36189793, 2022). "Our finding provides novel insights into the mechanism by which KAT6B regulates glioma progression by STAT3." (PMID 35432536, 2022). "CD163+p-STAT3+ clustering also occurred and was significantly more frequent within tumor areas of metastases than in gliomas." (PMID 35316217, 2022). "Polyomavirus and adenovirus infections are also associated with glioma development, and adenovirus infection promotes GBM stem cell formation through the TLR9/NEAT1/STAT3 pathway." (PMID 36497459, 2022). "Western blotting also showed that overexpression of STAT3 reduced the expression of E-Ca and increase the expression of N-Ca, vimentin, and Snail in glioma cells in response to TMEM158 knockdown." (PMID 34992215, 2022). "Recently, hypoxic glioma-derived exosomes containing IL-6 and miR-155-3p were shown to activate the STAT3 pathway leading to autophagy which induced M2 polarization and promoted glioma progression." (PMID 35267626, 2022). "Past studies reported that IL-6 directly influences the invasion of gliomas by activating the STAT3 pathway." (PMID 36605437, 2022). "The results indicated that LINC00346, CD204, and STAT3 were expressed higher in grade IV gliomas than in grade II gliomas, suggesting that the amount of M2 macrophage in different grades of gliomas was positively correlated with the expression." (PMID 36311792, 2022).